CD276 (CD276 molecule)
Diseases named in the same sentence as CD276 in open-access papers (continued):
Sharing a sentence is not in itself a finding about the gene and the disease.
cancer (continued). "They found that CD274 is highly expressed by cancer stem cells of mouse and human head and neck squamous cell carcinoma, and anti-CD276 could eliminate these stem cells." (PMID 34722635, 2021). "Thus, even in aerobic environments, cancer cells still produce energy by metabolizing glucose into lactic acid (anaerobic glycolysis), which is called Warburg effect and this is promoted by CD276." (PMID 33842369, 2021). "However, the precise molecular mechanisms for the functional role of CD276 in cancer remain elusive." (PMID 27329595, 2016). "B7-H3, also known as CD276, is a co-stimulatory molecule that may act as an antigen-specific inhibitor of T-cell mediated anti-tumoral immunity in human cancers." (PMID 23708103, 2013). "However, plasma from donor 7 showed a very distinct phenotype of exosomes carrying higher levels of EGFR, HER2, CD276 and osteopontin; all known cancer antigens." (PMID 24009888, 2013). "As a member of B7 family which consists of immune regulatory ligands, CD276 could modulate T lymphocyte activation and differentiation, recent studies have revealed that CD276 induces a robust immune evasive effect when deregulated in cancers." (PMID 38561369, 2024). "The combined hazard ratio (HR) for these 11 cancer types evaluating CD276 expression is 1.22 (95% CI: 1.06–1.42, P < 0.001) and together with the mTORC1 score is 1.23 (95% CI: 0.99–1.53, P = 0.058), suggesting that the combined CD276 expression and mTORC1 score is an indicator of poor prognosis." (PMID 36869048, 2023). "Additionally, CSNK1D showed a positive correlation with TNFRSF25 and CD276 in most cancers." (PMID 37688771, 2023). "In addition, CD276 inhibition was able to reverse HNSCC cancer stem cells and metastasis." (PMID 36268020, 2022). "The CAFDL signature was significantly positively associated with TGFB1, CD276, CD40, VEGFA, VEGFB, etc., but showed significantly negative correlation with immune checkpoints (such as CD274, PDCD1, CTLA4, TIGHT, and HAVCR2) and anti-cancer immune regulators (IFNG, IDO1, and GZMA)." (PMID 35967425, 2022). "In addition, UBE2C was correlated with CD276 in many cancers." (PMID 34950739, 2021). "Consequently, it can be inferred that CD200‐positive or CD276‐positive cancer stem cells may orchestrate metastatic latency through immune evasion." (PMID 33932112, 2021). "B7-H3 (CD276), an immune checkpoint protein, is overexpressed in malignant tumors, while its expression in normal tissues is low, and several B7-H3-targeting therapies are under clinical evaluation." (PMID 41751851, 2026). "Advanced-stage cancers had decreased levels of ICOS expression, and tumors with high ratios of PD-L1/ICOS, PD-L2/ICOS, or CD276/ICOS expression have a worse prognosis and a worse prognosis for patients with positive lymph nodes." (PMID 40661938, 2025). "The B7 homologous 3 (B7-H3), also known as CD276, is a transmembrane protein commonly expressed by cancer cells that act as an immune checkpoint, allowing cancer cells to evade immune surveillance." (PMID 39995659, 2025). "We also noted consistent induction of CD95, CD276/B7-H3 and CD340, all known targets of therapeutic approaches in cancer." (PMID 40374812, 2025). "B7-H3, also called CD276, is a B7 family protein that functions as a T-cell regulator that is overexpressed in many cancers including SCLC." (PMID 40507328, 2025). "Future research endeavors are essential to elucidate the mechanisms underpinning B7-H3-mediated apoptosis in macrophages, its regulatory pathways, and the influence of CD276 on macrophage behavior and cancer phenotypes." (PMID 40801642, 2025). "CNIH4 was also observed to be significantly positively correlated with multiple immune checkpoints, including CD276, CD86, and PDCD1, in cancers such as KIRC, KIRP, and LGG." (PMID 40051704, 2025). "Subsequent analysis also demonstrated a clear relationship between GPX4 expression and key immune checkpoints such as VEGFB, TGFB1, CD276, TNFRSF18, and TNFRSF4 across most cancer types." (PMID 41142608, 2025).
cancer (continued). "In the present study, we evaluated the expression of the immune checkpoints CD276, CD44, TNFRSF14, and VSIR across a range of cancer tissues." (PMID 40727469, 2025). "B7-H3 (CD276), a member of the B7 family, is regarded as a promising candidate for immunotherapy in cancer treatment." (PMID 40666622, 2025). "Our vehicle comprises a cancer-selective cfos promoter, TNBC-targeting anti-CD276 mAb and the packed AAV carrying the cmLumiOpto genes." (PMID 41462289, 2025). "One of the molecular targets for radionuclide diagnosis and therapy is B7-H3 (known as CD276), which is overexpressed in various cancers, whereas its expression is low in most normal organs and tissues." (PMID 41098568, 2025). "As its expression is reportedly upregulated in cancer tissue, several CAR constructs targeting CD276 are already in the clinical testing phase (e.g., NCT05835687 and NCT04077866)." (PMID 40469103, 2025). "B7-H3 (CD276), a member of the B7 immune checkpoint family, plays a critical role in modulating immune responses and has emerged as a promising target in cancer therapy." (PMID 40214484, 2025). "There is also a significant correlation between RAB3B expression and immune scores in various types of cancers, as well as a significant positive correlation between RAB3B expression and CD276 in 22 types of cancer." (PMID 38688977, 2024). "A phase I trial enrolling patients with different cancers, including RCC, has evaluated vobramitamab duocarmazine (MCG018), an ADC that targets B7-H3 (CD276)." (PMID 38668075, 2024). "Several inhibitory immunoreceptors, including but not limited to CD28, CD80, CD86, CTLA4, CD276, and CD274, have been identified and studied in cancer in recent decades." (PMID 38831187, 2024). "Our comprehensive analysis revealed that PLEK2 expression was significantly associated with various immune regulatory genes across multiple cancer types, including CD276 (B7-H3), CD274 (PD-L1), and FAS." (PMID 39546161, 2024). "B7-H3, also known as CD276, belongs to the B7 family and is generally expressed in various human cancers." (PMID 39093344, 2024). "In pan-cancer, HMGB1 had the highest positive correlation with NUDT21, followed by TLR4, CD276, and TNFRSF4." (PMID 38349866, 2024). "The immune checkpoint molecule B7-H3, also known as CD276, belongs to the B7-CD28 family and is overexpressed in various malignant tumors, correlating with prognosis." (PMID 39184916, 2024). "We have identified frequently used markers for the determination of cancer cells and CSCs: Axl, CD44, CD90, CD117, CD276, EGF, PD-L1, PD-1, Sox2." (PMID 38664641, 2024). "Our analysis revealed that elevated PLEK2 expression was significantly associated with increased expression of several key immune checkpoint molecules, such as CD276 (B7-H3), CD274 (PD-L1), LGALS9, PVR (CD155), and FAS across a wide spectrum of cancers." (PMID 39546161, 2024). "Our findings indicated a significant relationship between LOXL2 expression and the majority of the genes in immune checkpoint pathways, like VEGFA, CD276, TGFB1, and IL10 in pan-cancer." (PMID 38922489, 2024). "Our analysis indicated a positive correlation between B3GNT5 and immune activation markers, including CD276, PVR, NT5E, STING1, and TNF-SF18, as well as immunosuppressive genes TGF-ΒR1, IL-10PR, KDR, CD274, PDCD1LG2, IL-10, and IDO1 in the pan-cancer cohort." (PMID 39671359, 2024). "The B7-H3 (also known as CD276), member of the B7 immune checkpoint protein family, is overexpressed in cancer cells, thus promoting tumorigenesis." (PMID 38501058, 2024). "This is the first study to investigate the significance of the lateral interaction between CD147 and CD276 in CSCs, shedding light on the functional role of CD147 and its proximal proteins in cancer cell stemness." (PMID 37648771, 2023).
cancer (continued). "For immunomodulators, we found that the KIFscore was positively correlated with ULBP1, MICB, and CD276, while it was negatively correlated with TNFSF13 and TNFRSF14 in the vast majority of cancers." (PMID 37711200, 2023). "And especially, USP28 was significantly correlated with NRP1, CD276, ADORA2A, and TNFSF15 in most cancers." (PMID 37450415, 2023). "B7-H3, also known as CD276, is a molecule of the B7 superfamily, whose overexpression was correlated with cancer progression." (PMID 37569276, 2023). "In the present study, our analysis has shown that CD276 expression was positively correlated with a number of immune checkpoint genes, including TGFBR1, TGFB1, NECTIN2, IL10RB and CSF1R, in most types of cancer." (PMID 36717836, 2023). "Thus, CD276 may be an important immunological target in cancer." (PMID 37373167, 2023). "In addition, CD276 was found to be associated with nonspecific immunomodulatory effects, such as neutrophil degranulation and signaling by interleukins, in certain types of cancer, including KICH, LAML, LGG, LIHC, PCPG, READ, STAD and UVM." (PMID 36717836, 2023). "In most TCGA cancers, except for SARC and TGCT, there was a strong positive correlation between USP28 and CD276 and Neuropilin-1 (NRP1)." (PMID 37450415, 2023). "The immune immunomodulators CD276 (B7-H3) and SIRPA (SIRPα) demonstrated increased expression in the stroma of high-grade dysplasia and carcinoma regions." (PMID 36442992, 2023). "PDCD1, CD274, CTLA4, LAG3, C10orf54, and BTLA expression had positive correlations in most cancer types, and in approximately half of the cancer types, GBP1 expression is positively correlated with CD276 expression." (PMID 35222540, 2022). "B7-H3 (CD276), a member of the B7 family that plays an immunoregulatory role in the T cell response, has been highlighted as a novel potential target for cancer immunotherapy." (PMID 36284349, 2022). "The immune inhibitor CD276 and VEGFA correlated positively with KIF11 in most human cancer types, but VEGFB correlated negatively with KIF11 in most human cancer types." (PMID 36742345, 2022). "According to the correlation analysis between SRSF3 and immune checkpoint gene expression, it can be found that SRSF3 is closely related to TNFSF14, TNFRSF14, TNFRSF25, CD276, NRP1, VSIR in a variety of malignant tumors (P <0.05)." (PMID 35494088, 2022). "The genes included in the high-expression group were VTCN1, CD200, CD276, and LGALS9, as they showed a higher expression level in all the cancer samples." (PMID 36157232, 2022). "We then determined the exact pathway which controls the cancer stem cell–specific immune checkpoints CD200 and CD276." (PMID 33932112, 2021). "Confirming the role of CD276 in macrophage recruitment as well as in modulation of PAI-1 and uPA in cancer patients’ samples is essential to validate our data." (PMID 34290311, 2021). "That also means that cancer stem cells with high TGF‐β, Hedgehog, and Wnt signaling activation are able to display high levels of CD200 and CD276 expression, thus escaping from immunosurveillance." (PMID 33932112, 2021). "It has been found that B7-H3 (CD276), EIFs, Rabs, CTGF mRNA increased in sEVs derived from different kinds of cancer cells affected by different dose and duration of ionizing radiation." (PMID 34906146, 2021). "B7-H3 (also known as CD276) is a newly identified member of the B7 family, which is found in several human cancer cells and APCs." (PMID 33747915, 2021). "CD48, CD200 and VISTA are also downregulated in cancer samples, while CD276, LGALS9 and PVR are upregulated in cancer tissue." (PMID 33806327, 2021). "CD47, enabling the escape of cancer cells from macrophage-mediated phagocytosis, CD276 (B7-H3) and CTLA4, two immune checkpoint molecules involved in inhibition of immune response, were progressively increased." (PMID 33276569, 2020).
cancer (continued). "Nevertheless, specific lysis rates for these non-malignant targets after co-incubation with CD276-directed CAR NK-92 cells were less than half of those observed with the cancer cells." (PMID 40469103, 2025). "Additionally, GLO-1 expression demonstrated strong associations with both inhibitory and stimulatory ICPs, such as CD276, VEGFA, and HMGB1, across a majority of the analyzed cancer tissues." (PMID 40727469, 2025). "Additionally, MATN3 tends to positively correlate with genes such as CD276, NT5E, and TMEM173 in most cancers." (PMID 41004439, 2025). "HLA-I surface expression of target cells correlated negatively with respective cell lysis, which can explain the different lysis rates observed for cancer and non-malignant cell lines with comparable CD276 expression." (PMID 40469103, 2025). "Strong and consistent positive correlations were witnessed between ADM and several immune checkpoint genes, including CD274 (PD-L1), CD276, TNFRSF18, TNFSF9, and PVR in pan-cancer analysis, indicating its role in the development of suppressive immune microenvironment and T cell exhaustion." (PMID 40529377, 2025). "ADM was found to exhibit a strong and consistent positive correlation with several immune checkpoint genes, including CD274 (PD-L1), CD276, TNFRSF18, TNFSF9, and PVR in the pan-cancer analysis, which contributed to the development of a suppressive immune microenvironment." (PMID 40529377, 2025). "These proteins, including ICAM-1, SPPL2A, CD276, and CD44, may help the cancer cells stick together, spread, and avoid the immune system." (PMID 40805206, 2025). "Indeed, early studies reported the immunsuppressive effects of several possible immune checkpoints, including CD276, Siglec-15, B7x, HHLA2, and PD-L2 in patients with PD-L1lo/– cancer." (PMID 40985894, 2025). "Through the coordination with membrane-associated glycoproteins—including CD44, epidermal growth factor receptor (EGFR), integrins, CD280 (uPARAP/Endo180/MRC2), and CD276, CD147 orchestrates intracellular signaling events that drive cancer cell metabolic adaptation." (PMID 41479915, 2025). "Furthermore, CD276 inhibits cancer cell responses to doxorubicin (DOX) via the AKT/TM4SF1/SIRT1 pathway, while knocking down B7-H3 promotes cell senescence upon DOX treatment." (PMID 40214484, 2025). "However, it was noteworthy that among these immune-related genes, CD274, CD276, TNFRSF18, TNFSF9, and PVR displayed strong correlations with ADM expression across almost all cancer types." (PMID 40529377, 2025). "Moreover, we described 5 genes associated with hypoxia high status, of which the top 3 (LGALS3, CD276 and NT5E) have already been identified as targets of interest in cancer." (PMID 38510243, 2024). "From a pan-cancer perspective, ARPC1A expression was positively correlated with VEGFB and CD276." (PMID 38911374, 2024). "Furthermore, the expression of CD276, MICB, PVR, TGFB1, and TGFBR1 displayed high correlations with TUBA1B expression in most cancers." (PMID 38589634, 2024). "ENST00000311534 was significantly correlated with HMGB1, ENST00000326094 was significantly correlated with BTN3A1, CD160, TGFBR1, and IL6R, and ENST00000375991 was significantly correlated with CD276, ENTPD1, HMGB1, TLR4, KDR, and TGFBR1 among these 33 immune genes in more than 20 cancer types." (PMID 39766805, 2024). "Correlation analysis between RFC4 and checkpoint gene expression in different types of cancers showed a high correlation with immune genes including CCL4, CCL16, HLA family genes, TNFRSF8, TNFRSF14, TNFRSF18, CD70, CD44 (p < 0.05), CD276, CX3CL1 and VGEGFA (p < 0.05)." (PMID 39031628, 2024). "A cancer stem cell (CSC) sub-cluster was selected among 12 cancer cell sub-clusters due to an enrichment in stem cell marker expression, such as CD44, CD98, CD47, and CD276." (PMID 39409886, 2024). "Interestingly, our study showed a concordant indication by presenting a positive correlation between CD276 and PODNL1 expressions in pan-cancer." (PMID 37504302, 2023).
cancer (continued). "B7-H3 (CD276), a member of the B7 family of proteins, is a key player in cancer progression." (PMID 36859240, 2023). "The use of combination therapy (anti-CD276 antibody and anti-PD1/PD-L1 antibody) for cancer treatment may be promising." (PMID 37373167, 2023). "The TIMER2 dataset revealed that CD276 was negatively correlated with the infiltration levels of CD8+ T cells and B cells, whereas CD276 expression was positively correlated with macrophages and neutrophils in TCGA in pan-cancer." (PMID 36717836, 2023). "It is worth noting that IL12RB1, CD276, and APBB1IP are involved in cancer surveillance, inhibition of T-cell mediated responses, and T-cell recruitment, respectively, whereas CA11 may induce proliferation and invasion of gastrointestinal tumors." (PMID 37228491, 2023). "Based on the CIBERSOFT dataset, CD276 was found to be negatively correlated with CD8+ T cells, B cells and T cells, whereas CD276 expression was positively correlated with macrophages and neutrophils in numerous types of cancer." (PMID 36717836, 2023). "Taken together, based on our systematic analysis, our findings have revealed important roles for CD276 in different types of cancers, especially GBM, and CD276 may potentially serve as a biomarker for cancer." (PMID 36717836, 2023). "CD276 has been reported to increase HIF-1α expression and promote the glycolysis of cancer cells." (PMID 35783506, 2022). "While CD276, ENTPD1, IDO1, LGALS9, and VSIR were commonly detected in the Stereo‐seq samples, only IDO1 and LGALS9 seemed to have higher and wider expression in the CSCC samples than in the non‐cancer samples." (PMID 35986392, 2022). "In diverse cancer types, correlation analysis between CDCA4 and checkpoint gene expression indicated a high connection (P<0.05) with TNF-related immune genes including TNFRSF8, TNFRSF14, TNFRSF18, CD70, CD44, and CD276 (B7-H3)." (PMID 35251007, 2022). "In addition, we investigated the relationship between FASN and immune checkpoint gene expression and found that FASN was significantly positively correlated with the immune checkpoint genes CD276 and VEGFA in as many as 27 cancer species." (PMID 36555243, 2022). "Compared to other immune checkpoints, CD276 affects immunity, as well as regulates the cancer cell aggressiveness via multiple non-immune pathways." (PMID 36338975, 2022). "Besides, there was a robust positive relationship between PDIA3 and CD276 and Neuropilin-1(NRP1) in most of the TCGA cancers." (PMID 35401558, 2022). "Interestingly, CD276, NRP1, and TNFSF4 expressions were significantly negatively correlated with SHC1 in various cancers." (PMID 35601500, 2022). "CD276 is an immune checkpoint molecule in the epithelial-mesenchymal transformation (EMT) pathway, which plays a crucial part in the cell proliferation, invasion, and migration of malignant tumors, and is a promising therapeutic target for tumors." (PMID 36451774, 2022). "We confirmed it as a biomarker of M2 macrophage infiltration in various cancers and speculated that JMJD8 mediated the CSC immunity surveillance, M2 macrophage polarization, and CD8+ T-cell depression induced by CD276." (PMID 35898493, 2022). "Notably, pan-cancer correlation analysis between PBK and CD276 was conducted using the mRNA expression data from TCGA." (PMID 33431797, 2021). "Next, we wondered whether a subpopulation of cancer cell stems have the dual capabilities of resistance to the innate and adaptive immune system through synchronous expression of CD200 and CD276." (PMID 33932112, 2021). "CD276 was selected for further investigation based on its significant role in the course of other types of cancer and on a lack of literature reports about its role in development and course of MTC." (PMID 34680929, 2021). "Collectively, our findings describe a novel PBK/MSL1/CD276 signaling axis, which may play an important role in immune evasion of NPC and may be targeted for cancer immunotherapy." (PMID 33431797, 2021).